ABO (ABO, alpha 1-3-N-acetylgalactosaminyltransferase and alpha 1-3-galactosyltransferase)
Diseases named in the same sentence as ABO in open-access papers (continued):
Sharing a sentence is not in itself a finding about the gene and the disease.
COVID-19 (continued). "Among these three, only ABO and IL-6R proteins had some evidence of genetic colocalisation with posterior probabilities (PP.H4) more than 0.9 and 0.4, respectively, of a shared genetic signal between protein and COVID-19 phenotype." (PMID 34402426, 2021). "At the time of writing, 34 case/control studies reporting associations between ABO phenotypes and the risk of COVID-19 have been reported, while only four studies failed to uncover a significant association." (PMID 33499228, 2021). "Together with the present observations on anti-Tn antibodies, this may explain the ABO effect on COVID-19 epidemiology." (PMID 33643275, 2021). "Finally, if there is an effect of ABO blood groups on SARS-CoV-2 infection or the outcome of COVID-19, its impact on the evolution of the pandemic in different regions of the world and its potential importance in terms of patients care remain to be assessed." (PMID 33499228, 2021). "Moreover, COVID-19 patients have lower levels of anti-ABO antibodies than control individuals, suggesting that these antibodies are protective only when present in sufficient amounts." (PMID 33499228, 2021). "Indeed, for some of these, there is already direct evidence of implication with SARS-CoV-2 infection or with the evolution of COVID-19, such as ABO (blood groups) and ACE2 (a key human receptor for SARS-CoV-2)." (PMID 33981715, 2021). "Hence, we performed a case-control study to explore the relationship between the ABO blood group and COVID-19 in Wuhan and further classified the populations according to gender." (PMID 32793517, 2020). "A recent genome-wide association study (GWAS) reported that two polymorphisms, the rs11385942 insertion/deletion polymorphism of the leucine zipper transcription factor-like protein 1 (LZTFL1) gene and the rs657152 SNP of the ABO gene, are related to severe COVID-19 cases with respiratory failure." (PMID 33396837, 2020). "Moreover, recent studies demonstrate the involvement of chromosome 3p21.31 (rs11385942) and chromosome 9q34.2 (rs657152) implying the ABO blood group in disease's behavior in patients with respiratory failure infected with COVID-19." (PMID 33424917, 2020). "Together, these findings suggest that ABO antigens may interplay with pathogenesis of COVID-19; however, the mechanism(s) by which these molecules confer susceptibility or protection is subjected to speculations." (PMID 38624532, 2020). "Lower risk of COVID-19 in patients with blood type O may have contributed to the hypothesis that certain blood types may be more protective against SARS-CoV-2 infection, perhaps by anti-glycan ABO antibodies." (PMID 40012912, 2024). "Indeed, our study lacks blood group and HLA data from hospitalized, deceased and asymptomatic COVID-19 patients, which would be of interest given that there could be a significant link between ABO and severity." (PMID 36844192, 2023). "Shared genetic variants contributed to the causality, where rs10490770 in LZTFL1 suggested direct causality (SNPs → COVID-19 → CHD), and SNPs in ABO (rs579459, rs495828), ILRUN (rs2744961), and CACFD1(rs4962153, rs3094379) may simultaneously influence their risks." (PMID 37964352, 2023). "ABO(H) glycans on the viral S protein or lung epithelial cells may impact viral infection, while ABO(H) antigens on von Willebrand factor (vWF) and coagulation factor VIII (FVIII) are known to impact thromboembolic risk, which may impact COVID-19 disease severity." (PMID 36696414, 2023). "The two variants with eQTL effects in monocytes of the COVID-19 patients had significant eQTL effects specifically in cMono (FDR = 2.6 × 10−6 for ABO and FDR = 0.017 for IFNAR2), and no such eQTL effect of the IFNAR2 variant was observed in the healthy controls (FDR = 0.66)." (PMID 37095364, 2023).
COVID-19 (continued). "The first GWAS analysis with 1980 patients with COVID-19 identified two loci associated with the most severe forms of COVID-19: one locus was 3p21.31, which includes the genes SLC6A20, LZTFL1, CCR9, FYCO1, CXCR6, and XCR1, while the other was 9q34.21, including the ABO blood group." (PMID 35455670, 2022). "Note that deleterious variants in ABO often lead to blood groups A and B, which is consistent with the epidemiological association that non-type-O individuals are at higher risk of COVID-19." (PMID 36327219, 2022). "As a result of examining relationship between ABO genotype determined from GWAS data and the onset of COVID-19, individuals with blood type O were found to be less likely to develop COVID-19, and individuals with blood type A were more likely to develop COVID-19." (PMID 35264675, 2022). "However, in one study, it was suggested the ABO rs912805253 variant as a risk factor for SARS-CoV-2 infection rather than the risk of hospitalization or death from COVID-19." (PMID 35062298, 2022). "It is still not well-known how the ABO locus regulates COVID-19 susceptibility." (PMID 35634344, 2022). "Thus, differences in ABO blood group phenotypes may partly explain the observed heterogeneity in COVID-19 severity patterns, and could help identify individuals at increased risk." (PMID 34978705, 2022). "Thus, our findings may explain the susceptibility to infection in the early stages of the disease, whereas other factors such as 3p21.31 gene cluster and the ABO blood-group system may determine terminal status of COVID-19." (PMID 35636966, 2022). "Our study could not find an association between the ABO blood group and specific outcomes of COVID-19, including pneumonia, ICU admission, severe disease, the need for oxygen, and death." (PMID 36013335, 2022). "In particular, a GWAS study on Italian and Spanish patients identified two susceptible loci of severe COVID-19 including one locus on chromosome 3 with multiple genes included (SLC6A20, LZFTL1, CCR9, CXCR6, XCR1, FYCO1), and the other on chromosome 9 that defines the ABO blood types." (PMID 36292769, 2022). "The relationship between an ABO blood type and susceptibility to COVID-19 is not straightforward, therefore individually relating each ABO blood type to the virus attack rate may be misleading." (PMID 33499228, 2021). "Finally, the AncestryDNA COVID-19 host genetic study identified COVID-19 genetic associations with SLC6A20, LZTFL1 variants on the chromosome, ABO locus on chromosome 9 and a novel association on chromosome 11 that includes Polypeptide N-Acetylgalactosaminyltransferase 18 (GALNT18)." (PMID 34575070, 2021). "The distribution of the ABO blood groups among our study participants was similar to that in the South Indian population, indicating that the ABO blood groups had no role in the susceptibility to COVID-19." (PMID 34888199, 2021). "Furthermore, the present study could provide a platform for research into the relationship between the ABO blood groups and COVID-19 at a molecular level, which could uncover potentially vital information regarding new mutations currently ravaging India." (PMID 34888199, 2021). "This could be the reason why one GWAS study failed to reveal a signal of association between COVID-19 and the ABO locus." (PMID 33499228, 2021). "Our findings suggest that in more advanced stages of the pandemic, individual genetic factors, and specifically the overall distribution of ABO and Rh blood groups distribution in the specific population, might exert a stronger influence on COVID-19 transmissibility and severity." (PMID 34972836, 2021). "Comparison of ICU interventions, complications and outcomes for COVID-19 patients admitted to VGH ICU between March 30 2020 and March 31 2021 based on ABO blood group." (PMID 40173171, 2025).
COVID-19 (continued). "We found a significant positive genetic correlation of VTE with COVID-19 hospitalization and identified specific shared loci for VTE with each COVID-19 trait in ABO, ADAMTS13 and FUT2 genes, which was involved in coagulation." (PMID 37085521, 2023). "In line with previous studies, we identified ABO gene and FUT2 gene, which contributed to both VTE and COVID-19." (PMID 37085521, 2023). "Plasma proteins including AAT, ABO, APP, FGA, HPX, ITIH4, PON and others showed similar or higher observation frequency in NHP compared to COVID-19." (PMID 37031181, 2023). "Our meta-analysis supports that the effects of variation within the ABO and ATXN2 genes are shared between COVID-19 and asthma." (PMID 35386719, 2022). "However, a later genome-wide association study (GWAS) of severe COVID-19 with respiratory failure reported two clusters of genes associated with two different polymorphisms: rs11385942 in leucine zipper transcription factor like 1 gene (LZTFL1) and rs657152 in the ABO gene." (PMID 35636966, 2022). "This ‘coloc-first’ approach identified four proteins (ABO, FAS, OAS1, THBS3) with evidence of genetic colocalisation (PP.H4 >0.8) with four out of seven COVID-19 phenotypes." (PMID 34402426, 2021). "Similarly, a study from the UK aimed at relating ABO phenotypes to the risk of COVID-19 in pregnant mothers, reported the results of separate analyses of White and BAME (Black, Asian, Minority Ethnic) women, the latter being overrepresented among the COVID-19 positive cases." (PMID 33499228, 2021). "ABO and FUT2 all contribute to both autoimmune diseases and COVID-19." (PMID 38400850, 2024). "Among these TWAS significant genes, ABO (enriched in artery aorta and shared by EOC with all three COVID-19 phenotypes), CRHR1-IT1 (enriched in artery aorta and prostate), and PLEKHM1 (enriched in brain cortex) were located at pleiotropic loci identified in cross-trait meta-analysis." (PMID 37636041, 2023). "An alternative hypothesis is Renin-Angiotensin-System (RAS) unbalancing, where RAS-pathway genes, including rs495828 in ABO, was suspected predictive of CHD complications of COVID-19." (PMID 37964352, 2023). "The cross-trait and co-localization analyses identify 2, 3, and 4 shared loci between venous thromboembolism and severe COVID-19, COVID-19 hospitalization, SARS-CoV-2 infection respectively, which are mapped to ABO, ADAMTS13, FUT2 genes involved in coagulation functions." (PMID 37085521, 2023). "Accordingly, data from a recent meta-analysis do not confirm a relationship between ABO blood group and COVID-19 mortality." (PMID 35364749, 2022). "Though several publications have indicated a role of ABO blood typing in COVID-19 acquisition and severity, this was not the case for us and similar other studies." (PMID 37092112, 2022). "Our findings support the notion that some genetic variants, most notably at the ABO and PPP1R15A loci, in addition to SLC6A20, can indeed affect susceptibility to infection rather than progression to severe COVID-19 once infected." (PMID 34237774, 2021). "The consensus that emerged is that the association ofCOVID-19 with the ABO locus is highly significant and the risk of SARS-CoV-2infection and possibly also COVID-19 severity is slightly lower for group O thanfor non-O groups." (PMID 34436508, 2021). "Therefore, ABO/Rh blood group system does not support a predictive model of immunogenicity of the BNT162b2 vaccine, just as ABO/Rh screening should not be used as a triage mechanism in COVID-19." (PMID 35893819, 2022). "Whereas ABO antibodies in the saliva may not contribute to the pathogenesis of COVID-19, individual pre-existing high serum concentrations of anti-A/anti-B may have a protective effect against SARS-CoV-2 infection." (PMID 35956128, 2022). "Hence, this study does not limit itself to identify ABO links with COVID-19, but investigated comorbidities reported in a population sample that were admitted to hospitals in the UAE with confirmed SARS-CoV-2 infection." (PMID 35096865, 2021).
COVID-19 (continued). "However, the present study demonstrates that ABO and Rh subgroup distributions are similar among the Turkish COVID-19 patients with and without a positive PCR test result and lung involvement." (PMID 33936883, 2021). "We found no appreciable differences among ABO by demographic, lifestyle, and COVID-19 exposure." (PMID 34639344, 2021). "Therefore, in this prospective study, we aimed to investigate ABO antibody levels, including IgM, IgG and IgA isotypes, in the serum and saliva of non-hospitalised patients who recovered from mild COVID-19 and to compare them with those of individuals who had never been infected with the virus." (PMID 35956128, 2022). "Against this background, in the present study, we further investigated the effect of HDACIs on the expression of ABO, as well as that of ACE2 and TMPRSS2, in cultured epithelial cell lines, to determine whether HDACIs could have a potential preventive effect against COVID-19." (PMID 33564039, 2021).
malaria (80 papers, 2006 to 2025). Malaria is a serious and sometimes fatal disease caused by a parasite that commonly infects a certain type of mosquito which feeds on humans. "In conclusion, our study among a Moroccan military contingent deployed in the CAR did not demonstrate a statistically significant association between ABO or Rh blood groups and the incidence, recurrence, or severity of malaria." (PMID 40821228, 2025). "Host genetic factors, including ABO and Rh blood groups, are theorized to negatively affect the susceptibility and severity of malaria illness." (PMID 40821228, 2025). "Here, we mainly focus on seven blood type systems significantly associated with malaria, which are: ABO (ISBT 001), located on chromosome 9q34.2, encodes glycosyltransferases that synthesize carbohydrate antigens (A, B, H) on glycoproteins and glycolipids." (PMID 41450567, 2025). "The ABO blood group system has been extensively studied in people in relation to malaria susceptibility." (PMID 41471183, 2025). "We also noted that a correlation exists between the ABO blood type and susceptibility to certain infectious diseases, including malaria; blood group A and B antigens resemble α-Gal." (PMID 39523648, 2024). "Reports from various studies regarding the potential association between ABO blood groups and malaria risk in different populations are contradictory." (PMID 39371587, 2024). "The associations between ABO phenotypes and malaria are linked to the disease's pathogenesis, and a deeper understanding of these interactions is essential for exploring the glycobiology of malaria." (PMID 39371587, 2024). "We next examined the relationship between ABO genotype and susceptibility to severe malaria in the case-control study." (PMID 37708213, 2023). "Our finding that the ABO gene dose affects rosetting supports our prediction that AA/BB/AB individuals will be at higher risk of severe malaria than AO/BO individuals." (PMID 37708213, 2023). "If ABO genotype influences malaria susceptibility via a mechanism related to rosette size and microvascular obstruction, we would predict that ABO genotype associations would only be demonstrated in severe disease, and not in mild or asymptomatic infections." (PMID 37708213, 2023). "ABO genotype was determined in a case-control study on susceptibility to severe malaria involving >5000 Kenyan children, while ABO blood group phenotypes were assessed on a sub-group of 2761 control children." (PMID 37708213, 2023). "The ABO system was discovered in the year of 1901 and afterward, an association between the ABO blood system and diseases such as malaria, hemolytic disorders, cancer, and life expectancy was suggested." (PMID 35735664, 2022). "Studies on the role of human genetic factors and diseases show an association between human susceptibility to malaria and the ABO blood group." (PMID 36050680, 2022). "Several studies have reported the relationship of the ABO blood group system to susceptibility and resistance of excessive Plasmodium parasite invasion in severe malaria." (PMID 34222663, 2021). "This overlap is driven by well-known genetic variation in the beta-hemoglobin gene (HBB) and ABO blood type affecting malaria risk but also by genetic variation in ATP2B4 which encodes a calcium transporter." (PMID 34001247, 2021). "The ABO blood group antigens have also been implicated as determinants of malaria susceptibility, as blood group O appears to offer some degree of protection." (PMID 32732983, 2020). "Genome-wide association studies have identified 4 genetic determinants of severe malaria risk in this population (ABO blood group, HbS, Dantu blood group, and ATP2B4)." (PMID 32536341, 2020). "Even though a prospective study would have been important in determining the effect of inherited blood disorders on malaria, this cross-sectional study demonstrated association between ABO, G6PD and haemoglobin type on malaria in Kenyan children." (PMID 32646433, 2020).